MME (membrane metalloendopeptidase)
Diseases named in the same sentence as MME in open-access papers (continued):
Sharing a sentence is not in itself a finding about the gene and the disease.
neuropathy (5 papers, 2009 to 2025). A disorder affecting the nervous system that manifests with pain, tingling, numbness, and/or muscle weakness. "Dominantly inherited mutations in MME gene (p.C143Y) have also been associated to neuropathies with cerebral involvement (spinocerebellar ataxia)." (PMID 35212467, 2022). "The identification of pathogenic variants in well-established neuropathy-associated genes such as PMP22, MME, MPV17, and HINT1 confirms the value of CES, particularly when traditional single-gene screening is inconclusive." (PMID 41509941, 2025).
periodontitis (5 papers, 2020 to 2025). An acute or chronic inflammatory process that affects the tissues that surround and support the teeth. "MME and TSPAN11, two characteristic genes associated with PIGFs, may become targets for the treatment of periodontitis in the future." (PMID 40370461, 2025). "MME has never previously been studied in OTM; however, one previous study reported that MME mRNA levels were upregulated in periodontitis-affected gingival tissues compared with healthy tissues and that MME expression was detected in neutrophils and fibroblasts in those tissues." (PMID 36635354, 2023). "Additionally, we identified two genes (MME and TSPAN11) associated with this subpopulation that may be involved in the pathogenesis of periodontitis by promoting immune cell recruitment and exacerbating the immune response." (PMID 40370461, 2025). "Differential gene analysis, WGCNA, and machine learning algorithms identified two genes (MME and TSPAN11) as potential therapeutic targets for periodontitis." (PMID 40370461, 2025). "LASSO regression and RF, two machine learning algorithms, were finally utilized to determine the two best signature genes (MME and TSPAN11) that are highly related with the onset or progression of periodontitis." (PMID 40370461, 2025). "Notably, MME and TSPAN11 were identified as key genes associated with this specific GFs subpopulation that may drive disease progression by exacerbating the inflammatory response, suggesting their potential as therapeutic targets for periodontitis." (PMID 40370461, 2025).
cervical carcinoma (4 papers, 2016 to 2022). A carcinoma arising from either the exocervical squamous epithelium or the endocervical glandular epithelium. "Notably, HOXC6 plays an important anti-apoptotic role by regulating BCL-2 expression in human head and neck squamous cell carcinoma and cervical cancer, and suppressing NEP/MME and IGFBP-3 genes in prostate cancer." (PMID 31013831, 2019).
esophageal squamous cell carcinoma (4 papers, 2015 to 2024). Esophageal squamous cell carcinoma (ESCC) is a type of esophageal carcinoma (EC) that can affect any part of the esophagus, but is usually located in the upper or middle third. "As a type II transmembrane glycoprotein, MME participates in various significant biological processes and usually serves as a tumor suppressor in tumors, such as prostate carcinogenesis and esophageal squamous cell carcinoma." (PMID 37585411, 2023). "For example, downregulated MME was correlated with advanced tumor stage, and overexpression of MME interrupted the FAK-RhoA axis to inhibit tumor cell metastasis in esophageal squamous cell carcinoma." (PMID 37585411, 2023). "In esophageal squamous cell carcinoma, MME inhibits the focal adhesion kinase (FAK)- Ras homolog family member A (RhoA) signaling axis to interrupt tumor cell adhesion and metastasis, with a high MME expression level representing a favorable prognosis." (PMID 37585411, 2023).
infertile (4 papers, 2015 to 2022). "Membrane metallo-endopeptidase (MME) was uniformly overexpressed (>2 fold) in all infertile groups." (PMID 26321892, 2015).
myeloma (4 papers, 2015 to 2025). "Consistent with our proteomic findings, in relapsed myeloma patient tumor cells we found significant transcript decreases of CD53 and EVI2B, while MME (CD10) showed a significant increase." (PMID 35840578, 2022).
neuroendocrine tumor (4 papers, 2008 to 2024). "In a different study, MEN1 and DAXX were shown to repress the expression of the membrane metalloendopeptidase (MME) and mutations in MEN1 or DAXX result in loss of this repression leading to neuroendocrine tumor proliferation." (PMID 30315258, 2018).
non-small cell lung carcinoma (4 papers, 2009 to 2025). A group of at least three distinct histological types of lung cancer, including non-small cell squamous cell carcinoma, adenocarcinoma, and large cell carcinoma. "While most of these genes were up-regulated by hypoxia also in NSCLC cell lines, membrane metallo-endopeptidase (MME, neprilysin, CD10) expression was not increased in hypoxia in NSCLC cell lines, but in carcinoma-associated fibroblasts isolated from non-small cell lung cancers." (PMID 24460801, 2014).
dementia (3 papers, 2017 to 2024). Loss of intellectual abilities interfering with an individual's social and occupational functions. "Targeted re-sequencing of the six candidate genes (LTF, MME, UBE4A SORL1, FAM221A and KDM2B) was performed in 35 EOAD cases with a family history of dementia." (PMID 28595629, 2017).
emphysema (3 papers, 2006 to 2025). "Moreover they produce elastolytic enzymes, e.g. metalloproteinases such as macrophage elastase (MME), that may degrade the extracellular matrix and thus contribute to the development of parenchymal damage and thereby to pulmonary emphysema in COPD." (PMID 17137518, 2006). "Here, MMP-12 (also termed macrophage metalloelastase MME) has been identified to be of foremost importance in lung destruction, since MMP-12 knockout mice are resistant to smoke induced emphysema, while emphysema can occur independent of MMP-9." (PMID 23720629, 2013).
lymphocytic leukemia (3 papers, 2010 to 2020). "The most downregulated gene was Membrane Metallo-Endopeptidase (MME), also known as common acute lymphocytic leukemia antigen, CALLA, CD10 or NEP, that is highly expressed in mature germinal center B-cells." (PMID 20706582, 2010).
membranous nephropathy (3 papers, 2015 to 2021). "A small number of infants presenting with a clinical picture of CNS may have congenital membranous nephropathy due to a maternal variant in the MME gene, which encodes the podocyte protein NEP." (PMID 33514942, 2021). "Absence of MME gene product in the mother resulted in the development of membranous nephropathy in the fetus because maternal anti-MME antibodies bound to MME on fetal podocytes." (PMID 26536600, 2015). "MME was also a podocytic antigen that was responsible for human membranous nephropathy (MN)." (PMID 26536600, 2015).
atherosclerosis (2 papers, 2003 to 2019). A disease characterized by the build-up of fatty material and calcium deposition in the arterial wall resulting in partial or complete occlusion of the arterial lumen. "Finally, ACP5, MRAP2, and MME were found to show associations with both atherosclerosis and lncRNA-H19." (PMID 30778327, 2019).
diabetic nephropathy (2 papers, 2015 to 2024). "MME, also known as neprilysin, has been implicated in various pathological conditions, including diabetic nephropathy." (PMID 39338303, 2024). "Expression of MME at mRNA levels was significantly down-regulated in kidneys of patients with diabetic nephropathy (DN)." (PMID 26536600, 2015).
Insulin resistance (2 papers, 2019 to 2024). Increased resistance towards insulin, that is, diminished effectiveness of insulin in reducing blood glucose levels. "Corticotropin releasing hormone binding protein (CRHBP), ARHGEF15, MME, MAP1A, FGF13, and SHANK3 are novel biomarkers for the development of insulin resistance." (PMID 30678306, 2019).
kidney stone (2 papers, 2013 to 2025). "Five of these protein ratio pairs positively promote kidney stone development: BAIAP2/MME protein level ratio, GRPEL1/MME protein level ratio, HLAE/IL15 protein level ratio, CEACAM1/GGT1 protein level ratio and BTN2A1/IL18BP protein level ratio." (PMID 40673688, 2025).
lupus nephritis (2 papers, 2023 to 2024). Glomerulonephritis in the context of systemic lupus erythematosus. "In the comparison of 62 subgroups, the up-regulated gene (PTPRC, MX1) and the down-regulated DEGs (EGR1, MME, RORC, ZBTB16, FKBP5) were verified to have mostly consistent change trends in all Lupus Nephritis vs. Normal Kidneys group with the results of GSE200306." (PMID 39301055, 2024).
preeclampsia (2 papers, 2024 to 2025). Preeclampsia is a hypertensive disorder of pregnancy that is characterized by new-onset hypertension with proteinuria presenting after 20 weeks of gestation, and depending on mild or severe forms may initially present with severe headache, visual disturbances, and hyperreflexia. "Further analysis of gene regulatory networks, including transcription factor–gene, gene–microRNA, and drug–gene interactions, revealed that seven hub genes (HK2, SRSF10, SOD1, ERO1L, IRF3, MME, and SH3BP5) were strongly associated with preeclampsia." (PMID 40966654, 2025). "Constructed a protein–protein interaction (PPI) network, identifying 10 hub genes, seven of which (HK2, SRSF10, SOD1, ERO1L, IRF3, MME, and SH3BP5) were strongly linked to preeclampsia." (PMID 40966654, 2025).
cerebral small vessel disease (1 paper, 2025). Cerebral small vessel disease is the term currently used to pathological processes that affect the brain parenchymal circulation (arterioles, capillaries, and veins). "Further, consistent with findings that AD and VaD often co-exist, our AD TWAS identified genes that were associated with lacunar and ischemic strokes, as well as cerebral small vessel disease in other studies, including SLC39A13, RAPSN, MAF1, and MME." (PMID 40141087, 2025).
Charcot-Marie-Tooth neuropathy (1 paper, 2020). "The MME gene codes for membrane metalloendopeptidase, one of enzymes whose dysfunction is associated with Charcot-Marie-Tooth neuropathy." (PMID 32050523, 2020).
Fanconi anemia (1 paper, 2023). Fanconi anemia (FA) is a hereditary DNA repair disorder characterized by progressive pancytopenia with bone marrow failure, variable congenital malformations and predisposition to develop hematological or solid tumors. "Among these 14 pathways, four major pathways were enriched: SNARE interactions involved in the vesicular transport (BET1 and STX6), leishmaniasis (FCGR1A, CYBB, and FOS), hematopoietic cell lineages (FCGR1A, ITGA3, MME, and CD5) and Fanconi anemia pathway (SLX4, ATR, and TELO2)." (PMID 37601105, 2023).
hearing loss (1 paper, 2020). "Indeed, MME mRNA was found to be expressed in hair cells and possibly in SG, but the protective potential of MME inhibition against AT or age-dependent hearing loss has not yet been tested." (PMID 32327991, 2020).
high-grade glioma (1 paper, 2018). "Finally, we analyzed the expression of p16, NGFR, WT1 and MME in 37 DIPG patient samples with H3.3K27M mutation and 58 non-brainstem pediatric high-grade glioma (NBS-HGG) samples with wild type H3.3 using the public database." (PMID 29932419, 2018).
male infertility (1 paper, 2015). The inability of the male to effect fertilization of an ovum after a specified period of unprotected intercourse. "MME and FAM3D along with ROS levels in the seminal plasma may serve as good markers for diagnosis of male infertility." (PMID 26321892, 2015).
minimal change disease (1 paper, 2025). "Notably, three proteins—ACAT1, MME, and FBP1—with the highest expression levels observed in minimal change disease (MCD) showed kidney tissue specificity." (PMID 40283082, 2025).
tumor (562 papers, 1978 to 2026). "The MME gene is located on human chromosome 3q21-27, which functions as a tumor suppressor and is linked to a number of malignancies." (PMID 40370461, 2025). "VCAM1 is one of five genes (CXCL12, MMP2, MMP11, VCAM1, and MME), which were associated with tumor progression, angiogenesis, and metastasis." (PMID 31731625, 2019). "Five of these genes, CXCL12, MMP2, MMP11, VCAM1, and MME, which have previously been associated with tumor progression, angiogenesis, and metastasis, clearly discriminated between primary BC and BCBM." (PMID 27340107, 2016). "We found that hypoxia led to overexpression of a stem-cell marker with elastase activity, membrane metallo-endopeptidase (MME), in tumor fragments, which was attributable to carcinoma-associated fibroblasts, not the neoplastic cancer cells." (PMID 24460801, 2014). "We performed clinical verification of MME, one of the tumor-associated proteins with significantly high fold changes in proteomics data, in individual plasma samples from controls and early stage GBC cases and found significantly increased levels in early stage GBC cases." (PMID 34876625, 2021). "We observed that Cluster2 and Cluster4 were primarily composed of LG-ESS, and notably, LG-ESS tumor cells (MME+) were mainly located in Cluster4." (PMID 39676856, 2024). "CD10, a membrane metalloendopeptidase, is found on CD10+ fibroblasts, which have been observed to promote specific tumor cells." (PMID 37686288, 2023). "MME was also found to be required for proliferation of the neuroendocrine cells that were co-repressed by MENIN and DAXX, and in vivo experiments proved that knockdown of MME suppressing the tumor growth." (PMID 35360859, 2022). "The SPI was calculated based the prognostic model, including BOC, GRIA3, MME, SPOCK1, and KNSTRN, which were associated with stemness, TNM stage, prognosis, and tumor microenvironment (TME)." (PMID 35360859, 2022). "Alterations in expression levels of genes, such as LOX, ATP5L, GALNT3, and MME revealed by large-scale sequencing were confirmed between cell lines as well as in tumor specimens with different ERBB2 backgrounds." (PMID 21731642, 2011). "Several genes thought to play a role in the processes of invasion, tumour progression and metastasis (MME, STAT3, DCBLD2, S100A10, CD9, S100A8) were highly downregulated in the NE vs the non-NE tumour group." (PMID 18827820, 2008). "Additionally, our study identified the tumor cell subgroup Str1, characterized by MME+ (gene of CD10 protein) expression, through a combination of H&E and miF staining." (PMID 39676856, 2024). "Tumour-like CAFs (tCAFs): We observed strong differential expression of proliferation-, migration- and metastasis-associated genes (e.g., PDPN, MME, TMEM158 and NDRG1) as well as stress-response-associated genes (e.g., ENO1), and GAPDH in a small cluster (n = 786 cells)." (PMID 37463917, 2023). "MME is usually downregulated in cancers and serves as a tumor suppressor." (PMID 37585411, 2023). "Thus, its interesting to note that several genes thought to play a role in the processes of invasion, tumour progression and metastasis (MME, STAT3, DCBLD2, S100A10, CD9, S100A8) were highly downregulated in the NE vs the non-NE tumour group." (PMID 18827820, 2008). "Clinical verification of three tumor-associated proteins with elevated levels in comparison to all the three control types—5′-nucleotidase isoform 2 (NT5E), aminopeptidase N (ANPEP) and neprilysin (MME) was carried out using individual plasma samples from early or advanced stage GBC." (PMID 34876625, 2021). "Three proteins, NT5E, ANPEP and MME, were selected for clinical verification based on differential abundance in GBC compared to all control types (healthy, GSD and XGC cases), their association with tumor state in other cancers and functional relevance to tumor condition." (PMID 34876625, 2021).
tumor (continued). "Although various genes such as ADCYAP1, HAND2, MME, and RASSF1A have been reported to exhibit abnormal methylation and tumor development in UCEC, the role of CCND2 gene methylation in UCEC has not been reported." (PMID 40678058, 2025). "MME works in tandem with PTEN, a tumour suppressor, to control the activities of prostate progenitor cells and ultimately suppress PC progression." (PMID 36354023, 2022). "Moreover, CD10 (MME) positive myCAFs were found as a novel tumor suppressed CAF subclusters, while KLF4 positive and TIAM1 positive iCAFs were considered as tumor promoted CAF subclusters." (PMID 40303408, 2025). "As expected, NB5t primary cells showed increased expression of mesenchymal genes (NT5E, ENG, ACTA2, MME, CD44, VIM or ALPL), while NB5t tumor sample expressed mostly neuronal genes (TH, ENO2, NCAM1, DDC or CHGB) reflecting the neuroblastic phenotype of stage 4/M NB tumors." (PMID 29163787, 2017). "Finally, many of the genes down-regulated by EZH2 GOF in this study that modulate ECM-adhesion/signaling display altered expression or have been ascribed roles in tumor biology (e.g. NRCAM, CEACAM1, SORCS1, ADAM23, MME)." (PMID 25671303, 2015). "Specifically, the NR3C2, ANPEP, and FCGRT genes were significantly upregulated in tumor tissues, while PIK3R1, MME, SCD, and SERPINE1 genes were notably downregulated." (PMID 41011246, 2025).
cancer (170 papers, 2005 to 2026). A tumor composed of atypical neoplastic, often pleomorphic cells that invade other tissues. "Two targets, CA9 and MME, were consistently identified across all three analyses, suggesting their central roles in formononetin-mediated anti-cancer effects." (PMID 41567641, 2025). "Seven of the identified HGs (HK2, SRSF10, SOD1, ERO1L, IRF3, MME, and SH3BP5) were associated with PE and various carcinomas." (PMID 40966654, 2025). "Cancer cell resistance of paclitaxel is characterized by low levels of both MME and PTEN, driving vascular invasion and metastasis." (PMID 39003454, 2024). "Consistent with our study, changes in membrane metalloendopeptidase (MME) expression have been identified in several types of cancers." (PMID 37585411, 2023). "For example, TP53BP2, CDK11A, MME and SEPT6 are mutated in MCF10CA1a cells and have strong correlations to a number of cancers." (PMID 25969993, 2015). "For example, MME/CD10 was down-regulated in the CD26+ G3 cancer cells, and both GSE datasets showed agreement (some expression was detected in the stromal cells of GSE6099)." (PMID 20021671, 2009). "MME, also known as neprilysin, was responsible for the catalytic inactivation of multiple peptides, including endothelin, and could attenuate the progression of certain human cancers." (PMID 40894071, 2025). "Cancer and ECRF24 cells were distinguished through the strong expression of CD10 (membrane metalloendopeptidase) and CD31, respectively." (PMID 34067456, 2021). "MYBL1, MME and LRMP, as key regulators of the cell cycle, have been identified as potential therapeutic targets for cancer." (PMID 28423735, 2017). "While expression of ACTA2 – a marker expressed by both myoepithelial cells and cancer-associated fibroblasts (CAFs) – significantly increased in CAS compared to normal stroma, expression of TP63, CHD3, MYH11, SERPINB5 and MME did not increase." (PMID 37391533, 2023). "Based on the total score, the top 20 tree shrew drug targets included several homologs of targets for cancer chemotherapy, including vascular endothelial growth factor receptor 2 (VEGFR2), membrane metallo-endopeptidase (MME), and the proto-oncogene tyrosine-protein kinase Yes (YES1)." (PMID 25105297, 2014). "MME could catalyze the activity of the PENT tumor suppressor protein and could inhibit the phosphoinositide 3-kinase/protein kinase B (PI3K/AKT) signaling pathway to reduce cell survival and migration in cancer growth." (PMID 36287961, 2022). "Among these proteins, MME, CDH1, APC, and CA9 have not been previously reported to be involved in anti-cancer regulations." (PMID 41567641, 2025).
adenocarcinoma (18 papers, 2005 to 2025). A common cancer characterized by the presence of malignant glandular cells. "High expression of MME was significantly associated with poorer survival in adenocarcinoma patients of series GSE13213 (P = 0.00025) and series GSE14814 (P = 0.029), and in the combined cohort including 182 patients (P = 0.000012)." (PMID 24460801, 2014). "Lack of MME and PTEN results in development of adenocarcinomas characterized by propensity for vascular invasion and formation of proliferative neuroendocrine clusters after castration." (PMID 32205838, 2020).